C1orf116 (chromosome 1 open reading frame 116)
Description:
Putative androgen-specific receptor.
Synonyms: SARG; FLJ36507; MGC2742; MGC4309
Tractability: Antibody: its Gene Ontology location is reachable by antibodies, with high confidence; the Human Protein Atlas places it where antibodies can reach.
Gene: Protein-coding gene on chromosome 1 (207,018,522 to 207,032,821, reverse strand). Ensembl gene ENSG00000182795.
Subcellular location: Cytoplasm
Subcellular location (Human Protein Atlas): Cytosol; Plasma membrane
Gene Ontology:
Molecular function: protein binding
Cellular component: cytoplasm; cytosol; extracellular exosome; plasma membrane
Genetic constraint (gnomAD): Loss-of-function variants: 8 observed, 10.72 expected, observed/expected ratio (o/e) 0.75, 90% interval 0.44 to 1.34. The upper end of that interval is the gene's LOEUF score, 1.34, which puts it in group 5 of 6, group 1 being the genes least tolerant of losing a copy. Missense variants: 659 observed, 653.99 expected, observed/expected ratio (o/e) 1.01, 90% interval 0.94 to 1.08. Synonymous variants: 238 observed, 258.3 expected, observed/expected ratio (o/e) 0.92, 90% interval 0.83 to 1.03.
Homologues: Orthologues: chimpanzee C1H1orf116 (98% identical), macaque C1H1orf116 (93% identical), pig C1orf116 (75% identical), rabbit C1orf116 (67% identical), guinea pig C1orf116 (67% identical), mouse AA986860 (63% identical), rat C13h1orf116 (62% identical), tropical clawed frog c2h1orf116 (33% identical), zebrafish zgc:158258 (19% identical), zebrafish si:ch73-184c24.1 (8% identical).
Diseases named in the same sentence as C1orf116 in open-access papers:
C1orf116 is named in the same sentence as 10 diseases in open-access papers, as found by Europe PMC text mining. Sharing a sentence is not in itself a finding about the gene and the disease. The quoted sentences say what the papers report.
prostate carcinoma (4 papers, 2017 to 2023). A carcinoma that arises from epithelial cells of the prostate gland. "An earlier study revealed downregulation of C1orf116 is associated with poor prognosis in patients with lung and prostate cancer." (PMID 37476073, 2023). "Patient gene expression data shows that reduced expression of C1orf116 is associated with poor prognosis in lung and prostate cancer (unadjusted Wilcoxon rank sum p-value <0.05)." (PMID 28651527, 2017). "Furthermore, they demonstrated that the decreased expression of C1orf116 was associated with poor prognosis in lung and prostate cancer patients, which is consistent with our results in CN-AML." (PMID 34123815, 2021). "C1orf116 is a novel EMT biomarker for prostate cancer, and our study showed 17-fold and 24-fold downregulation of this gene in taxane-resistant prostate cancer subtypes DUTXR and PC-3TXR, respectively." (PMID 37476073, 2023). "We demonstrate that knockdown of C1orf116 expression induced expression of mesenchymal genes in epithelial prostate cancer cell line PC3-epi cells, suggesting it as a candidate driver of the epithelial phenotype." (PMID 28651527, 2017). "We found that C1orf116 expression is decreased in metastatic lesions compared to localized tumors in prostate cancer patients." (PMID 28651527, 2017). "Clinical data from breast, prostate cancer and lung cancer patients also suggested that changes in expression of C1orf116 could have functional implications in disease progression." (PMID 28651527, 2017). "This shows that in addition to being a novel EMT regulator in prostate cancer, C1orf116 could have broad effects across multiple cancer types." (PMID 28651527, 2017). "We also identified C1orf116, TUBB2B are common genes in taxane-resistant prostate cancer subtypes." (PMID 37476073, 2023). "We found three groups of genes in the EMT differentially expressed list: a) known EMT genes (e.g. CDH1, ZEB1, TGFB, CDH2, VIM, TIMP1), b) EMT genes previously unknown in prostate cancer (LSR, S100A14, DPYSL3) and c) novel EMT genes (including C1orf116)." (PMID 28651527, 2017).
lung carcinoma (2 papers, 2017 to 2024). "Analogous to these findings, we observed reduced expression of C1orf116 among lung cancer patients with smoking habits." (PMID 28651527, 2017). "The low expression of C1orf116 is related to the poor prognosis of lung cancer." (PMID 39411374, 2024). "Likewise, C1orf116 expression decreased with increasing cancer grade in patients with lung cancer." (PMID 28651527, 2017).
breast carcinoma (1 paper, 2017). "In some breast cancer datasets expression of C1orf116 increased with increasing cancer grade." (PMID 28651527, 2017).
cancer (4 papers, 2017 to 2025). A tumor composed of atypical neoplastic, often pleomorphic cells that invade other tissues. "Through manual literature search, we identified that a subset of the C1orf116 module gene list have been shown to be associated with multiple cancer types." (PMID 28651527, 2017). "This suggested that in addition to expression changes in in vitro cell line models, changes in C1orf116 expression could potentially have a functional role in clinically-important disease progression in cancer patients." (PMID 28651527, 2017). "The up-regulation of genes like C1orf116 and uncharacterized loci (LOC124902513, LOC107985667, LOC100506358, LOC112268263, and LOC105375676) suggests unexplored pathways in cancer regulation." (PMID 40430278, 2025).
tumor (4 papers, 2017 to 2024). "For this, we identified gene expression studies with at least 150 patients that also had information on tumor grade and expression data for C1orf116 and were able to find breast, prostate, colorectal and lung cohorts." (PMID 28651527, 2017). "In addition, it was found that C1orf116 has a high weight and is closely related to the EMT process, which may be a key early event in tumor metastasis." (PMID 39411374, 2024).
C1orf116 also shares sentences with these, for which no sentence is quoted: follicular papillary thyroid carcinoma (1 paper); leukemia (1); Lymph Node (1); lymph node metastasis (1); thyroid cancer (1).